RN7SL396P (RNA, 7SL, cytoplasmic 396, pseudogene)
Gene: Miscellaneous RNA gene on chromosome 8 (119,862,662 to 119,862,956, forward strand). Ensembl gene ENSG00000244642.
Homologues: Orthologues: chimpanzee Metazoa_SRP (83% identical), rabbit Metazoa_SRP (74% identical), rabbit Metazoa_SRP (72% identical), pig Metazoa_SRP (71% identical), rabbit Metazoa_SRP (69% identical). Paralogues in human: RN7SL5P (73% identical), RN7SL4P (72% identical), RN7SL1 (71% identical), RN7SL2 (70% identical), RN7SL3 (70% identical), RN7SL767P (69% identical), RN7SL128P (67% identical), RN7SL674P (66% identical), RN7SL296P (65% identical), RN7SL752P (65% identical), RN7SL220P (64% identical), RN7SL480P (64% identical), and 698 more.